CD4 (CD4 molecule)
Diseases named in the same sentence as CD4 in open-access papers (continued):
Sharing a sentence is not in itself a finding about the gene and the disease.
COVID-19 (continued). "Since decreased CD4 on monocytes correlated with increased disease severity in this study, patients with severe COVID-19 may be unable to mount the required CD4-mediated activation of monocyte for viral clearance." (PMID 33375371, 2020). "Indeed, antibodies against the RBD region in S1 are elicited in the vast majority of COVID-19 patients along with robust CD4 T cell responses." (PMID 32818217, 2020). "Furthermore, a greater CD4+:CD8+ ratio in COVID-19 patients was observed in comparison with control individuals." (PMID 32916812, 2020). "In line with this, acute malaria infection has been shown to result in a strong polarization of CD4+ T cells while it can be speculated that there seems to be a polarization toward CD8+ T cells in COVID-19." (PMID 32983106, 2020). "A significant increase of LAG-3 and TIM-3 on both CD8+ and CD4+ T cells across all subpopulations in COVID-19 patients could be detected." (PMID 32983106, 2020). "Patients with severe COVID-19 and underlying DM had lower CD4+ T lymphocyte counts than did those with non-severe COVID-19." (PMID 33297431, 2020). "A recent meta-analysis study discovered that the severity among COVID-19 patients might correlate with higher levels of WBCs count and lower levels of lymphocyte, CD4+ T cells, and CD8+ T cells counts." (PMID 32822430, 2020). "Pathogenic Th1 CD4+ T cells co-expressing IFNγ and GM-CSF were found only in the ICU patients indicating that these cells play an important role in the hyperinflammatory response of COVID-19." (PMID 33042116, 2020). "The EM CD4+ T cell subset in COVID-19 even showed a significant decrease of TIGIT expression." (PMID 32983106, 2020). "In COVID-19 patients, a significant T cytopoenia was observed in circulating CD4+ and CD8+ T cells." (PMID 32793245, 2020). "Moreover, lower counts of T lymphocytes and their subsets (total CD3+ <200/μL, CD4+ <100/μL, and CD8+ <100/μL) were significantly associated with higher risk of in-hospital death due to COVID-19." (PMID 32695683, 2020). "There are still some knowledge gaps about CD4+ T cell loss in PLWH and COVID-19." (PMID 33384690, 2020). "Similarly, the frequency of CD69 was lower on PD1−LAG-3− and PD1−TIM-3− CD8+ and CD4+ T cells compared to the expression on double-positive T cells in COVID-19 and malaria patients." (PMID 32983106, 2020). "In summary, comparing the expression of different co-inhibitory molecules of CD8+ and CD4+ T cells in COVID-19 vs. malaria there is a transient increase of the expression of certain inhibitory receptors like LAG-3 and TIM-3 in COVID-19 in the overall context of acute immune activation." (PMID 32983106, 2020). "Indeed, a potential benefit of T cell responses was recently demonstrated in two clinical studies that found an inverse correlation between severe COVID-19 and lower CD4+ and CD8+ T cell blood counts on admission." (PMID 33182546, 2020). "Furthermore, a higher percentage of CD4+ CD45RA+ naïve cells and lower CD4+ CD3+ CD45RO+ memory T cells were also found in COVID-19 patients." (PMID 33193331, 2020). "Patients with severe COVID-19 and severe influenza A had a significantly lower number of total T cells (P = 0.001 and P < 0.0001, respectively), CD4+ T cells (P = 0.001 and P < 0.0001, respectively), and CD8+ T cells (P = 0.002 and P < 0.0001, respectively) than healthy controls in group two." (PMID 33261583, 2020). "Our findings indicated the expression profile analysis of CD4+ FoxP3+ CD25+ T cells could be a potential marker for the assessment of severity of COVID-19 patients." (PMID 33244382, 2020). "Indeed, patients with severe COVID-19 frequently have lower absolute numbers of Interferon-γ producing CD4+ T cells compared to patients with moderate disease." (PMID 32849623, 2020).
COVID-19 (continued). "COVID-19 patients have a reduction in absolute numbers of lymphocytes, including CD4+ and CD8+ T lymphocytes, which display markers related to activation or exhaustion/senescence, along with altered expression of master regulators and several chemokine receptors." (PMID 33291439, 2020). "Indeed, these data are consistent with earlier reports showing that lymphopenia in severe COVID-19 affects CD4+ T cells less than CD8+ T cells." (PMID 33101705, 2020). "In a similar way to chronic infections, COVID-19 might damage CD4+ T cells function and promote the excessive activation of CD8+ T cells with the subsequent potential exhaustion." (PMID 33182268, 2020). "On the other hand H5N1-related publications had similar rates of association for monocytes, CD8-positive, and CD4-positive T-lymphocytes to those in SARS, in all cases, lower than those in Coronavirus-related publications but higher than in COVID-19 related publications." (PMID 32746922, 2020). "Additionally, we also compared the peak levels of the clinical inflammation parameters C-reactive protein (CRP), IL-6, or ferritin with the expression of activation and inhibitory receptors on CD8+ and CD4+ T cells in COVID-19." (PMID 32983106, 2020). "A recent study showed that the CD4 + T-helper cells in the bronchoalveolar lavage fluid (BALF) of COVID-19 patients induce significant changes in gene expression and that the upregulated genes were enriched in pathways associated with pro-inflammatory cytokine of IFN-γ." (PMID 32876941, 2020). "Moreover, SARS-CoV-2-specific CD8+ and CD4+ T cells were detected in ~70% and 100% of COVID-19 convalescents, respectively." (PMID 32916812, 2020). "The targeting of thymus tissue by 2019-nCoV may be an important reason for the decrease in CD4+ Th cells in the peripheral blood of COVID-19 patients." (PMID 32976531, 2020). "In contrast, suppressed IFN-γ production by CD4+ T cells might be correlated with the disease severity of COVID-19." (PMID 33426096, 2020). "Early intervention and supportive treatment for patients whose age and CK, CD4, CD8 and C3 values are in high-risk ranges may have important significance in reducing the severity and mortality of COVID-19." (PMID 32866109, 2020). "The frequency of lymphopenia observed by us and others suggests that COVID-19 could act on lymphocytes, particularly T lymphocytes, with perhaps a depletion of CD4 and CD8 cells." (PMID 33033687, 2020). "Moreover, stimulation of peripheral blood mononuclear cells (PBMCs) from group of severe COVID-19 patients with peptides covering all viral proteins activated both CD4+ and CD8+ SARS-CoV-2-specific T cells." (PMID 32916812, 2020). "Additionally, patients with severe COVID-19 exhibited significant reductions in the peripheral blood lymphocyte, T lymphocyte, CD4+ T cell, and CD8+ T cell counts." (PMID 33240265, 2020). "In addition to the analysis of the traditional activation markers, we also looked at the expression of the co-stimulatory receptor CD226 on CD8+ and CD4+ T cells in COVID-19 and malaria patients compared to healthy individuals." (PMID 32983106, 2020). "In this study, we found that a decreased number of CD3+CD4+ lymphocytes was another risk factor for delayed negative conversion of SARS-CoV-2 in COVID-19 patients." (PMID 33256876, 2020). "Taking into account the percentages of the analyzed basic leukocyte subpopulations, similar statistical significances were observed for: T lymphocytes, CD4 cells, eosinophils as in the case of the absolute numbers analysis between COVID-19 X-ray (+) patients and heathy donors." (PMID 33291439, 2020). "Moreover, we found a rise in TNF-α-secreting CD8+ T cells as well as a similar tendency in CD4+ T cells obtained from COVID-19 patients." (PMID 32707842, 2020). "Additionally, circulating IL-6 levels are negatively correlated to monocyte HLA-DR expression, and both monocytes and CD4+ T cells were found to be circulating sources of IL-6 in COVID-19 patients." (PMID 32556942, 2020).
COVID-19 (continued). "Intriguingly, FURIN expression was increased in CD4+ T-cells from severe COVID-19 patients." (PMID 33178221, 2020). "Whether metformin could be a potential treatment strategy for CD4+ T cells lymphopenia in COVID-19 need further investigation." (PMID 33384690, 2020). "The CD4+ T cells’ cross-reactivity to the S protein might represent the key for understanding the different disease manifestations of COVID-19, particularly in the asymptomatic infections in children and adolescents." (PMID 32717854, 2020). "Thus, CD4-mediated SARS-CoV-2 infection of CD4+ T helper cells may contribute to a poor immune response in COVID-19 patients." (PMID 40429912, 2025). "Additionally, breast milk from women recovered from COVID-19 was observed to be enriched with antigen-experienced T cells, evidencing that most of the breast milk CD4+ and CD8+ populations were central memory T cells (CD45RO+/CCR7+), regardless of the time of milk expression." (PMID 40141241, 2025). "Conversely, the significantly higher CD4+ T cell responses at 4 weeks after the second booster in the non-COVID-19 group suggested that vaccine-induced T cell immunity may play a role in protection against SARS-CoV-2 infection and progression to severe disease." (PMID 41251472, 2025). "Participants with CD4+ counts below 200 cells/mm3 in our study showed lower IgG antibody titers, which could suggest that their immune systems have difficulty responding to the COVID-19 vaccine." (PMID 40266154, 2025). "Notably, CD4+ T-cell counts were significantly lower in COVID-19 patients who developed cryptococcosis, suggesting that impaired cell-mediated immunity may contribute to the pathogenesis of this opportunistic invasive fungal infection (IFI)." (PMID 41190068, 2025). "Thus, our work confirms a positive association between CD4+ T cell count and COVID-19 vaccine immune response, but in a sample of Black and Hispanic adults, a population lacking in COVID-19 vaccine research." (PMID 40432125, 2025). "A CD4+ T-cell count < 200 cells per μL (p < 0.001), older age (p = 0.001), a vector-based primary vaccination series (p < 0.001), and increased time since the last COVID-19 vaccination dose or SARS-CoV-2 infection (p < 0.001) were associated with lower S1-specific IgG antibody levels over time." (PMID 40388467, 2025). "Additional studies in a small number of individuals suggested that pre-existing CD4+ and CD8+ T cells against alpha common cold coronavirus (229E) but no other seasonal coronaviruses were associated with protection from symptomatic and fatal SARS-CoV-2 infections in unvaccinated COVID-19 patients." (PMID 40266143, 2025). "However, contemporary data from novel mRNA vaccination trials, widely diffused since the COVID-19 pandemic, unveiled a significant and enduring response by both CD4+ and CD8+ T cells, contributing to sustaining protection even after neutralizing antibody decay." (PMID 38675732, 2024). "PWH hospitalised due to COVID-19 had higher CD4 + cell counts (380 cells/mm3 [IQR: 184–580] vs. 97 cells/mm3 [IQR: 34–272], p < 0.01) and a higher proportion of virologic suppression (VS) compared to those hospitalised due to non-COVID-19 causes (92% vs. 55%, p < 0.01)." (PMID 38789972, 2024). "In agreement with prior evidence linking short leukocyte telomeres to poor COVID-19 outcomes, our data implicate CD4+ T cell aging as a predominant driver for immunopathology in patients with advanced ages where additional age-related immune remodeling may have been plateaued." (PMID 38377029, 2024). "We next determined whether the low magnitudes of CCCs/SARS-CoV-2 cross-reactive CD4+ and CD8+ T-cell responses detected in unvaccinated severely ill and fatal COVID-19 patients was a result of an overall deficit in the frequencies of total CD4+ and CD8+ T cells." (PMID 38605956, 2024). "Therefore, we examined the role of CD4+ TEM cell clusters in COVID-19 in more detail." (PMID 39337460, 2024).
COVID-19 (continued). "UPPHI likely have different repertoires of protective and pathogenic memory CD4+ and CD8+ T cells targeting cross-reactive CCCs/SARS-CoV-2 epitopes of structural, non-structural, and accessory protein antigens that are associated with different disease outcomes in COVID-19 patients." (PMID 38605956, 2024). "Notably, CD4+ cytotoxic T-cells are essential for protective immune responses to viral infections and vaccines against pathogens such as Influenza A and others, and showed a strong enrichment in patients with COVID-19." (PMID 38049509, 2024). "However, a cohort study showed that HIV infection was an independent prognostic factor for poor outcomes of COVID-19 infection, suggesting that PLWH with low CD4+ T-cell counts experience a more severe COVID-19 clinical course than those who are HIV-seronegative." (PMID 39339957, 2024). "The concomitant and excessive upregulation of CD4+ T cells in the early symptomatic phase of COVID-19 may potentially indicate reduced clearance by the immune system via viral immune evasion and reduced activation of Tregs and B cells, as well as possible T-cell exhaustion." (PMID 38793691, 2024). "Due to the central role of CD4+ T cells in the polarization of the immune response and the control of chronic viral infections, more analyses are needed to evaluate the importance of CD4+ Th cell subsets in the development of different forms of acute or persistent COVID-19." (PMID 39257580, 2024). "They hypothesized that increased interferon gamma expression in CD4+ T cells, which has been reported to play a central role in COVID-19-related cytokine storms, may have triggered the activation of adaptive immune responses and initiated the formation of sarcoidal granulomas." (PMID 39403183, 2024). "Notably, MHC-II-expression has been widely detected in the inflamed lung epithelial and endothelial cells of patients with lethal COVID-19, suggesting that CD4+-CTL cells may cooperate with CD8+ T cells in killing SARS-CoV-2 infected cells." (PMID 39460293, 2024). "This suggests that the transient increase in CD4 cell frequencies may be associated with rapid priming of CD4 T spike-specific cells by COVID-19 vaccine, independent of ART." (PMID 39772028, 2024). "Moreover, altered frequencies of CD4+ and CD8+ T cell subsets including expansion of CD27- Tem, reduction of Tfh and Treg, increase of class-switched memory B cells, and loss of naive B cells were features of ASyS with severe or fatal COVID-19." (PMID 38500883, 2024). "Therefore, memory B cells with broadly cross-reactive neutralizing potential against βCoVs observed in MERS-recovered patients might be boosted by elevated CD4+ T cells induced by COVID-19 vaccination and/or SARS-CoV-2 infection." (PMID 38416834, 2024). "In contrast, a recent study conducted by the WHO Global Clinical Platform for COVID-19 found only modest reduction in mortality risk with Omicron compared to Delta infection among PLHIV, though this did not specifically comment on pregnant populations and cited risk factors of low CD4 and older age." (PMID 39321175, 2024). "In this study, the cytokine expression profile in children with COVID-19 was investigated by using six different intracellular monoclonal antibody markers post-SARS-CoV-2 stimulation on multiple SARS-CoV-2 T-cell subsets defined by CD4 and CD8 and one activation marker (CD137) with flow cytometry." (PMID 39594853, 2024). "Furthermore, there was no causal relationship between markers of PTB and COVID-19, suggesting heterogeneity of markers of CD4+ TEM cells across diseases." (PMID 39337460, 2024). "The observed association between CD4 cell count and COVID-19 vaccine is not an epiphenomenon; rather, vaccination may have a direct potentiating effect on cellular immune responses in PWH." (PMID 39772028, 2024).
COVID-19 (continued). "In addition, some of the PWH with advanced immunosuppression (pre-COVID-19 CD4 count 100–350 cells/uL) were included, so the increases in CD4 counts may be partly related to ART." (PMID 39772028, 2024). "Additionally, immune dysregulation in long COVID, particularly in individuals who had mild acute COVID-19, includes alterations in T-cells, such as T-cell exhaustion, reduced CD4+ and CD8+ effector memory cell numbers, and elevated PD1 expression on central memory cells, persisting for over a year." (PMID 38203577, 2023). "Thus, COVID-19 vaccine may help promote the activation of CD4 + T cell and reprogramming of the tumor microenvironment." (PMID 37679851, 2023). "In addition to the CD8+ T-cell defect, CD4+ T cells in COVID-19 cases also express the exhausted markers, and a high frequency of non-functional CD4+ T cells that are deficient at producing IFNγ, IL-2, and TNFα has been demonstrated in severe COVID-19 cases." (PMID 36839573, 2023). "Mechanically, IL-22 has been reported to be robustly expressed by SARS-CoV-2-specific CD4+ T cells, and IL-22 is closely related to tissue repair, especially in lung epithelial cells, suggesting that SARS-CoV-2 CD4+ T cell response may play an active role in lung tissue repair during COVID-19." (PMID 37601070, 2023). "Although data from the US National COVID Cohort Collaborative showed that a lower CD4 cell count among PWH is associated with a higher risk of adverse COVID-19 outcomes, PWH without virological suppression had an increased risk of hospitalization but not death." (PMID 36851791, 2023). "However, studies have revealed that PLWH adhering to cART, with adequate CD4+T cell count, viral suppression and without comorbidities do not have a higher risk of COVID-19 severity and mortality than non-PLWH." (PMID 37243203, 2023). "Moreover, following the successful resolution of mild COVID-19, tissue-resident memory CD4 T cells and CD8 T cells specific for SARS-CoV-2 have been found in the lungs of humans, indicating that virus-specific T cells do migrate to the lungs during the course of the disease." (PMID 37112761, 2023). "In addition, the two mRNA COVID-19 vaccines also induce cytotoxic CD4+ T cells (CD4-CTL)." (PMID 37388738, 2023). "Additionally, as a potentially fatal infectious condition, patients with COVID-19 have excessive suppression of inflammatory cytokines and impaired immune response by having reduced CD4 T and CD8 T cell counts, which allowed for the discovery of a fungal coinfection." (PMID 37799179, 2023). "Thus, the ALC could be a surrogate marker for CD4+ at early COVID-19 stage in low-resource settings." (PMID 37377785, 2023). "When patients are infected with COVID-19, a cytokine storm (releasing a large amount of several proinflammatory cytokines) often occurs and is followed by lymphopenia, functional impairment of CD4+ T cells, and a quantitative decrease in monocytes, eosinophils, and especially, CD3+ and CD8+ T cells." (PMID 38188702, 2023). "The proportion of clonally expanded CD4_Ef increased in moderate disease compared to healthy and severe group, suggesting that efficient clonal expansion of CD4_Ef might contribute to the prevention of serious COVID-19." (PMID 37095364, 2023). "Previous studies reported that neither the CD4 count nor HIV viral load was associated with the incidence of COVID-19 in PLWH, suggesting that PLWH with immunosuppression may have no increased risk of SARS-CoV-2 infection." (PMID 37964230, 2023). "Taken together, we presented that differentially expressed genes: CASP1, CD4, and EIF2AK3 might be considered as the diagnostic biomarker for COVID-19 and characteristic immunological infiltration could influence the systemic immune microenvironment in the pathogenesis of COVID-19." (PMID 37228369, 2023).